COL1A1 (collagen type I alpha 1 chain)
Diseases named in the same sentence as COL1A1 in open-access papers (continued):
Sharing a sentence is not in itself a finding about the gene and the disease.
scoliosis (6 papers, 2019 to 2024). A congenital or acquired spinal deformity characterized by lateral curvature of the spine. "Patients with pathogenic variants in COL1A1 or COL1A2 alone tended to have a milder form of scoliosis." (PMID 37730650, 2023). "The patient with c.805-2A > G (COL1A1) variant displayed severe skeletal deformity (type IV) including scoliosis and low bone density in the spine (Z score: −4.8)." (PMID 35154279, 2022). "Those in the non-COL1A1/1A2 group have significantly higher rates of scoliosis compared to those in the COL1A1/1A2 group (61.5% vs 40.4%, p = 0.04)." (PMID 39450342, 2024). "We found that COL1A2 appeared significantly less severe than COL1A1, with an OR of 0.28 (95% CI 0.1–0.71, p = 0.01) for progression into moderate or severe scoliosis." (PMID 37730650, 2023). "Since patients with COL1A1 and COL1A2 variants together constituted about 2/3 of the cohort, we asked if scoliosis severity was differentially affected by the two genes." (PMID 37730650, 2023). "Within the two collagen genes, COL1A2 was less damaging than COL1A1 in progressing into advanced stages of scoliosis." (PMID 37730650, 2023). "This analysis identified a group of SNPs of the COL1A1 gene having a protective effect towards scoliosis." (PMID 31536524, 2019). "Those in the non-COL1A1/1A2 group have higher rates of scoliosis compared to those in the COL1A1/1A2 group (62% vs 40%, p = 0.04), as well as higher rates of expressive language disorder/delay (15% vs 0.4% in non-COL1A1/1A2 and COL1A1/1A2 patients, respectively; p < 0.001)." (PMID 39450342, 2024). "This is an interesting finding because these genetic variants have never been reported before to be associated with scoliosis although several pathogenic variants of COL1A1 were previously associated with this spine abnormality." (PMID 31536524, 2019). "Nearly 90% of cases are caused by mutations in the collagen genes COL1A1/A2 (classical OI) leading to multiple fractures, scoliosis, short stature and nonskeletal findings as blue sclera, hypermobility of joints, bone pain and delayed motor function development." (PMID 31533771, 2019). "We found that patients with COL1A1 and COL1A2 genotypes were strongly biased towards having mild or no scoliosis at all, whereas patients with pathogenic variants on IFITM5, WNT1 and other recessive genes did not display such a pattern." (PMID 37730650, 2023). "Patients with either COL1A1 and COL1A2 were strongly biased toward having mild or no scoliosis, whereas patients with mutations in IFITM5, WNT1 and other recessive genes were more evenly distributed among the four outcome grades." (PMID 37730650, 2023). "However, it appears that the COL1A1/1A2 group has higher rates of scoliosis operations compared to the non-COL1A1/1A2 group, though not significant (19.4% vs 6.3%, p = 0.30)." (PMID 39450342, 2024).
vascular EDS (6 papers, 2019 to 2025). "The absence of classical UPR activation was also previously observed in other connective tissue disorders, such as in OI patients with mutations in COL1A1 disrupting triple helix formation and in vascular EDS patients carrying COL3A1 mutations." (PMID 31288483, 2019). "Among these subtypes, vascular EDS (vEDS), an autosomal dominant disorder, is linked to mutations in the COL3A1 and/or COL1A1 genes, which encode for type III and type I collagen, respectively." (PMID 41020269, 2025). "Of these, vascular EDS (vEDS) has an autosomal dominant inheritance pattern and is associated with mutations in the COL3A1 and/or COL1A1 genes, which encode type III and type I collagens, respectively." (PMID 38485809, 2024).
Breast Invasive Carcinoma (5 papers, 2019 to 2023). "TCGA analysis of TGF-β target genes (e.g., COL1A1, COL3A1, COL5A2, COL6A1, COL6A3, TIMP1, and CTGF) further identified overactivation of TGF-β signaling pathway in a broad spectrum of solid tumors, in particular in breast invasive carcinoma and pancreatic adenocarcinoma tissues." (PMID 37328484, 2023).
cholestasis (5 papers, 2015 to 2022). Impairment of the bile flow caused by obstruction within the liver, or outside the liver in the bile duct system. "RT-PCR demonstrated an notable decrease in mRNA levels of pro-fibrotic markers (α-SMA, Col1A1, vim and TGF-β1) by calcipotriol treatment in both BDL- and DDC-induced cholestasis." (PMID 32296329, 2020).
colon adenocarcinoma (5 papers, 2020 to 2024). "For example, in colon adenocarcinoma (CAC), COL1A2, THBS2, and COL1A1 were related to prognosis." (PMID 33178362, 2020).
communicating hydrocephalus (5 papers, 2019 to 2024). An abnormal accumulation of cerebrospinal fluid within the ventricles of the brain that occurs as a consequence of impaired cerebrospinal fluid reabsorption by the arachnoid granulations. "Mutations in COL1A1 have been associated with hydrocephaly suggesting an important role in the development of the neocortex rather than NSC development." (PMID 37728850, 2024). "Osteogenesis imperfecta, which is caused by mutations in the type 1 procollagen genes (COL1A1/COL1A2), is associated with communicating hydrocephalus." (PMID 31575827, 2019).
Crohn disease (5 papers, 2022 to 2025). A gastrointestinal disorder characterized by chronic inflammation involving all layers of the intestinal wall, noncaseating granulomas affecting the intestinal wall and regional lymph nodes, and transmural fibrosis. "In contrast, Ogr1 expression was found associated with increased Col1a1 mRNA in a mouse model of fibrotic lesions in Crohn’s disease suggesting a context-dependent mechanism of OGR1 function." (PMID 37373151, 2023). "These showed a marked increase in COL1A1 protein expression in both the narrowed sections of colons from Crohn's Disease patients and in human primary colonic fibroblasts treated with TINAGL1." (PMID 38750695, 2025). "After verifying COL1A1, CXCL10, MMP2 and FGF2 in samples from CD patients, to further verify the expression of these four genes in Crohn’s disease fibrosis, we prepared a rat model of CD fibrosis using TNBS." (PMID 37622114, 2023).
head and neck cancer (5 papers, 2016 to 2025). A primary or metastatic malignant neoplasm affecting the head and neck. "However, its role in head and neck cancer is not fully understood, and further research is needed to elucidate the specific mechanisms by which COL1A1 contributes to tumor progression and metastasis in this context." (PMID 39065771, 2024). "COL1A1, ITGB4 and VTN have been associated with radioresistance in different types of cancer, such as nasopharyngeal carcinoma, esophageal squamous cell carcinoma and head and neck cancer." (PMID 34211843, 2021). "In order to comprehensively recognize the role and potential mechanism of the COL1A1, IL1A, MMP9, and FN1 genes in the prognosis of head and neck cancer, we constructed a miRNA-related regulatory network in the current study." (PMID 39065771, 2024).
neurofibroma (5 papers, 2021 to 2025). An intraneural or extraneural neoplasm arising from nerve tissues and neural sheaths. "This is consistent with the observation that collagens such as COL1A1 and COL1A2, often associated with pro-fibrogenic skin fibroblasts, are downregulated in human neurofibromas." (PMID 37817770, 2023). "COL1A1 deposition is an integral part of neurofibroma formation." (PMID 34011935, 2021). "Although these pathways are believed to induce the proliferation of neurofibroma cells and COL1A1 production, leading to neurofibroma formation, the therapeutic outcomes of the specific mTOR inhibitor sirolimus and the anti-collagenogenic pirfenidone in clinical trials have not been satisfactory." (PMID 34011935, 2021).
pancreatic adenocarcinoma (5 papers, 2019 to 2025). "This was proven by transfecting this pancreatic adenocarcinoma cell line with cleavage-resistant COL1A1 (e.g., having mutations in COL1A1 776Pro; 777Pro or 774Pro and 776Met)." (PMID 37373151, 2023). "Survival analysis showed that NMU/Col1a1/YAP1 expression was associated with poor overall survival, and NMU expression was the highest in pancreatic adenocarcinoma patients with pancreatitis in TCGA." (PMID 31575084, 2019).
scleroderma (5 papers, 2013 to 2024). Scleroderma is a rare autoimmune connective tissue disorder characterized by abnormal hardening of the skin and, sometimes, other organs. "Especially IL-13, produced by CD8+CD28− scleroderma T cells, enhances COL1A1 protein expression in dermal fibroblasts." (PMID 29033951, 2017). "EGR3 is upregulated in the fibrotic dermis of mice with scleroderma, and increased EGR3 expression contributes to the upregulation of fibrotic genes such as ACTA2 and COL1A1." (PMID 37957540, 2024). "In accordance with the disease hallmarks, subtypes of collagen (COL1A1, COL6A1) were more highly expressed in scleroderma." (PMID 37443817, 2023).
squamous cell carcinoma (5 papers, 2017 to 2024). A carcinoma arising from squamous epithelial cells. "It has been reported that COL1A1 played a role in the proliferation, metastasis and invasion of oral squamous cell carcinoma cells." (PMID 36035989, 2022). "Only COL1A1 promoter revealed hypermethylation in NSCLCs (36%), which was particularly evident in squamous cell carcinomas (p = 0.024) and in the tumours with moderate-to-good differentiation (p = 0.01)." (PMID 28258342, 2017).
Stroke (5 papers, 2014 to 2025). Sudden impairment of blood flow to a part of the brain due to occlusion or rupture of an artery to the brain. "An increased expression of the newly identified stroke genes Il6ra, Il6st, S100a4, Stat1, and Stat2, but also the known genes Col1a1, Col1a2, Col3a1, has been implicated in blood vessel remodeling and contributes to vascular rarefaction, leakage, and intracranial aneurysms." (PMID 24672479, 2014). "We demonstrated that Col1a1-positive signals colocalised with Iba1-positive cells in the lesions of stroke patients." (PMID 40221393, 2025). "The Col1a1-GFP transgenic line has been used to identify a subset of perivascular cells that dramatically expand in number in response to a spinal cord injury that have the same characteristics of PSCs described in stroke injury." (PMID 27422020, 2016). "Transcription factor CoupTF2 (nuclear) was expressed by the Col1a1+ meninges (carets) and by Col1a1+ PSCs at P0 (arrows), P21 (arrows) and in the stroke lesion by PDGFrβ+ PSCs (arrows) but not by Ib4+ macrophages (carets)." (PMID 27422020, 2016).
thyroid cancer (5 papers, 2020 to 2025). "COL1A1 has similarly been implicated in promoting EMT and metastasis in other cancer types, such as colorectal and thyroid carcinomas." (PMID 40851082, 2025). "The miR-29b-3p inhibited thyroid cancer invasion and migration by regulating COL1A1 and COL5A1." (PMID 36829181, 2023). "Unsupervised clustering confirmed the target genes (LOX, p16, α-SMA, COL1A1, and FAP) upregulation in thyroid cancers and in particular in those with BRAF-like signaling (115 out of 206 BRAF-like tumors clustered in the 5-genes overexpressing group; p-value < 0.0001)." (PMID 31906302, 2020).
uterine sarcoma (5 papers, 2023 to 2025). "COL1A1 was considered to be associated with the pathogenesis of COL1A1-PDGFB fusion uterine sarcoma." (PMID 36925653, 2023). "The COL1A1-PDGFB fusion uterine sarcoma has invasive borders and is highly cellular, consisting of uniform cells with ovoid-to-spindle-shaped nuclei, minimal cytoplasm, and barely perceptible cell boundaries." (PMID 39064514, 2024). "LMS usually displayed moderate-to-severe nuclear heteromorphism, active mitoses, and remarkable necrosis and stained positive for the markers of smooth muscle differentiation, which were inconsistent with COL1A1–PDGFB fusion uterine sarcomas." (PMID 36994196, 2023). "With only five cases previously reported, we presented the sixth case of COL1A1–PDGFB fusion uterine sarcoma in the female genital tract." (PMID 36994196, 2023). "Postoperative RNA sequencing of tumor tissue was performed, which supported the diagnosis of COL1A1–PDGFB fusion uterine sarcoma." (PMID 36994196, 2023). "COL1A1–PDGFB gene fusion uterine sarcoma is an especially rare malignant mesenchymal tumor that was previously classified as an undifferentiated uterine sarcoma due to the lack of specific features of differentiation." (PMID 36994196, 2023). "The lesions were mostly located at the cervix instead of the corpus, which is the same for COL1A1–PDGFB fusion uterine sarcomas." (PMID 36994196, 2023). "Here, we presented the first uterine sarcoma located at the cervix with COL1A1–PDGFB gene fusion in China." (PMID 36994196, 2023). "Both histomorphologic manifestations and IHC staining of CD34 overlap with COL1A1–PDGFB fusion uterine sarcomas." (PMID 36994196, 2023). "Similar to COL1A1–PDGFB fusion uterine sarcomas, both were more common in the cervix and shared similar morphological manifestations." (PMID 36994196, 2023). "Other features such as vascular hyalinosis and hemangiopericytoma-like changes, vascular infiltration, and significant inflammatory cell infiltration are rarely seen in COL1A1–PDGFB fusion uterine sarcomas." (PMID 36994196, 2023). "Clinicopathological findings of COL1A1–PDGFB fusion uterine sarcoma in this case and comparison with previous cases in the literature." (PMID 36994196, 2023). "The rarity of COL1A1–PDGFB fusion uterine sarcomas occurring in the female genital tract and unspecific morphology, especially without molecular tests, resulted in frequent misdiagnosis." (PMID 36994196, 2023). "She presented with a cervical mass at the anterior lip of the cervix invading the vagina and was treated with laparoscopic total hysterectomy plus bilateral salpingo-oophorectomy (TH+BSO) and partial vaginal wall resection with the final pathology of COL1A1–PDGFB fusion uterine sarcoma." (PMID 36994196, 2023). "However, the age onset of COL1A1–PDGFB fusion uterine sarcomas was older, ranging from 43 to 82 years (average at 56.7 years, median at 53.5 years)." (PMID 36994196, 2023). "COL1A1–PDGFB fusion uterine sarcomas were often reported to be asymptomatic." (PMID 36994196, 2023). "The prognosis for COL1A1–PDGFB fusion uterine sarcomas does not seem optimistic so far, as two patients of the five cases reported before have died." (PMID 36994196, 2023). "The collagen type-1 alpha-1 (COL1A1) and platelet-derived growth factor beta chain (PDGFB) fusion uterine sarcoma is a relatively new entity that is not yet listed in the 2020 WHO classification of female genital tumors, with only a few cases reported." (PMID 39064514, 2024).
aneurysm (4 papers, 2017 to 2025). Bulging or ballooning in an area of an artery secondary to arterial wall weakening. "MicroRNA-513b-5p downregulation in ruptured aneurysms (RA) and unruptured aneurysms (UA) targeted COL1A1 and COL1A2 genes, regulating RIP1-RIP3-MLKL and MMP pathways to enhance cell death and apoptosis." (PMID 41342741, 2025). "Further analysis showed decreased SM α-actin+ area and mRNA expression levels of Acta2 and Col1a1 genes in aneurysms from Apoe−/−Light−/− mice, which are compatible with the loss of VSMC contractile phenotype." (PMID 34829747, 2021). "In addition, the miR-29 family is involved in aneurysm development by mediating extracellular matrix protein synthesis, including Col1a1, Col3a1, Col5a1, and Eln." (PMID 28164126, 2017). "In murine models of abdominal aortic aneurysms, miR-29b-3p upregulation accelerated aneurysm expansion and increased rupture rates, accompanied by decreased expression of key ECM targets (e.g., Col1a1, Col3a1, Col5a1, and Eln), while inhibition of miR-29b-3p reduced aortic aneurysm progression." (PMID 39767655, 2024).
atrial fibrillation (4 papers, 2017 to 2022). A disorder characterized by an electrocardiographic finding of a supraventricular arrhythmia characterized by the replacement of consistent P waves by rapid oscillations or fibrillatory waves that vary in size, shape and timing and are accompanied by an irregular ventricular response. "More specifically, miR-10a-5p overexpression was shown to promote COL1A1, COL1A3, α-SMA, and TGF-β1 protein expression and thus increased the levels of atrial fibrillation and cardiac fibroblasts in rat models." (PMID 35216219, 2022). "Atrial fibrosis, a significant feature of atrial fibrillation, was considered to result from disturbed extracellular matrix (ECM) metabolism with excessive fibrillar collagen including Col1a1 and Col3a1 deposition, generally in response to a cardiac insult." (PMID 34141473, 2021).
chondrosarcoma (4 papers, 2012 to 2025). A malignant cartilaginous matrix-producing mesenchymal neoplasm arising from the bone and soft tissue. "Additionally, we found expression of genes such as Collagen, type I, alpha 1 (COL1A1), Exostoses (multiple) 1 (EST1), Exostoses (multiple) 2 (EXT2), Vimentin (VIM), and Osteoprotegerin (TNFRSF11B), which are known to be involved in development of conventional chondrosarcomas." (PMID 22448124, 2012).
Chronic colitis (4 papers, 2022 to 2025). A chronic inflammatory disease of the large intestine (colon, cecum and rectum). "And immunohistochemical staining indicated an enhanced expression of Col1a1 in mice with chronic colitis induced by TNBS compared to the control ones." (PMID 35645830, 2022). "Moreover, fibrosis in the DSS-induced chronic colitis model was alleviated, as evidenced by a reduction in collagen volume fraction, and a decrease in Col1a1 and Col6a1 expression." (PMID 41334589, 2025). "Research indicates that daily oral administration of the anti-fibrotic drug GED decreases COL1A1 expression and improves intestinal fibrosis in DSS-induced chronic colitis in mice." (PMID 40607383, 2025). "DSS-induced chronic colitis attenuated biliary septal fibrosis, which may be attributed to less BA accumulation mediated inhibition of activated HSCs (Col1a1, Col1a2, Col3a1 and Timp1) without affecting PFs in Mdr2−/− mice." (PMID 37280200, 2023).
chronic kidney disease (4 papers, 2012 to 2026). Impairment of the renal function secondary to chronic kidney damage persisting for three or more months. "Naturally occurring fragments of collagen type I alpha 1 chain (COL1A1) have been previously associated with chronic kidney disease (CKD), with some fragments showing positive and others negative associations." (PMID 39740102, 2025). "Notably, the first COL1A1 fragments are consistently downregulated in chronic kidney disease (CKD), indicating an attenuation of endopeptidase‐mediated degradation of COL1A1." (PMID 39740102, 2025). "It has been reported that HIF-1α exerted an effect in hypoxia- and chronic kidney disease-induced fibrosis, while genetic knock-down of HIF-1α in renal epithelial cells led to a significant reduction in collagen deposition, including COL1A1 and COL3A1." (PMID 30536131, 2019). "RNA‐seq analysis of kidney organoids post 24 h heat stress at 41°C revealed no significant upregulation of COL1A1 or COL1A2, the genes encoding type I collagen, a key component of the fibrotic matrix in chronic kidney disease." (PMID 41573374, 2026). "The top 25 upregulated genes showed evidence of matrix protein replacement with increased collagen synthesis (Col1a1 and Col3a1) and cellular infiltration (Cxcl1, Lyzs, Ccl5, Lyz2, Lyz, C3 VCAM1 and Ear2), consistent with the histological presence of chronic kidney disease in the mice." (PMID 22970174, 2012).